FGF2 (fibroblast growth factor 2)
Diseases named in the same sentence as FGF2 in open-access papers (continued):
Sharing a sentence is not in itself a finding about the gene and the disease.
glioma (112 papers, 2000 to 2025). A benign or malignant brain and spinal cord tumor that arises from glial cells (astrocytes, oligodendrocytes, ependymal cells). "The IDH 1/2 mutation has a statistically significant effect on the FGF-2 concentration in G4 glioma, causing a decrease in the IDH 1/2 concentration." (PMID 38473833, 2024). "Examples of nuclear FGFs are FGF1, that stimulated DNA synthesis, and FGF2 that was associated with increased cell proliferation in glioma cells and invasion in pancreatic cancer." (PMID 34830836, 2021). "Nuclear activity of a heavy molecular weight FGF2 (hmwFGF2) has been implicated in promoting cell proliferation and survival in glioma, in glioma cells, and indirectly through nuclear localization in astrocytes." (PMID 34068954, 2021). "FGF-2 is implicated in brain tumor progression and localizes in the microvasculature as well as in the tumor cells in human gliomas." (PMID 32152825, 2020). "Previous studies revealed that HMW-FGF2 is primarily localized in nucleus whereas 18K-FGF2 resides in cytosol, and the nuclear FGF2 accumulation is associated with proliferation of human glioma cells." (PMID 26056081, 2015). "Similarly, we observed an increased microglia-mediated expression of FGF2 indicating angiogenic drive in the spheroids, which is known to be particularly maintained by glioma associated microglia, indicating the presence of this activated microglia type in the spheroids." (PMID 38317968, 2024). "For the test for determining VEGF-R2 and FGF-2 in glioma, a decrease in the concentration of the measured protein will indicate the disease because the direction of the diagnostic variable for these tests is decreasing (indicating a destimulant)." (PMID 38473833, 2024). "Previous studies have shown that FGF2 expression was transcriptionally suppressed by Dach1 in glioma cells and on the contrary, FGF2 was shown to activate DACH1 during skeletal development in mouse." (PMID 38581619, 2024). "Experiments on human glioma U251 cells showed that EPHA4 promoted fibroblast growth factor 2 (FGF2)-mediated cell proliferation and migration, along with increased MAPK and Akt phosphorylation stimulated by FGF2." (PMID 38612645, 2024). "Thus, the increased abundance of FGF2 could generate a feedforward loop, further driving/sustaining growth in hiPSCs, however that growth potential is also linked to breast and gastric cancers, as well as gliomas." (PMID 39540879, 2024). "High levels of FGF1 and FGF2 in glioma tissue contribute to angiogenesis, growth, invasion, and resistance to treatment of this cancer." (PMID 39201395, 2024). "The FGF-2 concentration was similar in stages G1 and G2, increased slightly with increasing grade of glioma malignancy, and was highest in CTR." (PMID 38473833, 2024). "In a medium containing the growth factors EGF and FGF-2 instead of serum, glioma cells show increased expression of stemness phenotype markers and can form spheres, just like normal neural stem cells." (PMID 38392188, 2024). "Glypicans are overexpressed in the glioma microenvironment when compared to normal brain tissue and, according to the literature, can stimulate glioma growth by inducing the upregulation of the FGF-2 signal." (PMID 36980765, 2023). "In glioma, inhibition of mPGES‐1 blocks angiogenic Akt‐fibroblast growth factor 2/TGF‐β/vascular endothelial growth factor signaling." (PMID 37180822, 2023). "Grown in the presenceof FGF2 on fibronectin-coated plates and in N2 medium with supplements,C6 glioma cells grown as NSPCs (referred to as C6DCs) formed uniformcultures of nestin-positive cells." (PMID 37647213, 2023). "FGF2 is overexpressed in human cancers, including gliomas, and acts as an autocrine and paracrine angiogenic factor." (PMID 35784465, 2022). "This purified antibody inhibited various biological functions of FGF2, such as proliferation/growth, migration and tube formation of human umbilical vein endothelial cells and apoptosis in glioma cells in vitro." (PMID 34830836, 2021).
glioma (continued). "After radiation, YAP was translocated into the nucleus, where it promotes the transcription and secretion of FGF2, which speeds up the proliferation of glioma cells by enhancing the DNA damage repair, similar to the effects of YAP." (PMID 34127812, 2021). "Taken together, these results suggest that FGF2 mediates the radioresistant effect of YAP on glioma cells." (PMID 34127812, 2021). "Consistently, we found that recombinant human FGF2 (rhFGF2) treatment promoted the proliferation and DNA repair of glioma cells but inhibited apoptosis after radiation, similar to the effects of YAP." (PMID 34127812, 2021). "Radiation activates YAP contributing to glioma cell growth via driving the expression of FGF2 and subsequently activating the MAPK–ERK pathway." (PMID 34127812, 2021). "FGF2 was expressed not only in the vascular epithelium but also in glioma cells, although the staining was weak." (PMID 34790962, 2021). "Altogether, reprogramming COX-2, mPGES-1 and CYP4A mediated-AA metabolism in glioma by flavonoid ISL inhibits the angiogenic Akt- FGF-2/TGF-β/VEGF signaling through ceRNA effect of miR-194-5p and lncRNA NEAT1." (PMID 31438982, 2019). "First, we have provided direct evidence that ISL is a potent COX-2, mPGES-1 and CYP4A11 inhibitor, and thereby blocks angiogenesis and induces vascular normalization in glioma through downregulation of FGF-2, TGF-β and VEGF." (PMID 31438982, 2019). "Lathia and colleagues also observed that symmetrical division of glioma stem cells in vitro depends on FGF-2 and that its removal favored differentiation." (PMID 27043632, 2016). "FGF-2 is effective at inducing Nestin, in C6 glioma cells, proving its contribution to the stemness of glioma cells." (PMID 26977157, 2016). "In glioma, FGF-2 contributes to maintenance of glioma stem cells and it is used in the media that support their growth." (PMID 27043632, 2016). "In other tumor types, such as gastric and esophageal cancer and pediatric glioma, intratumoral levels of FGF2 were shown to correlate with poor clinical outcome." (PMID 25609197, 2015). "Subsequent to the finding that glioma stemness was co-regulated by Twist1 and Sox2, normal neural stem cells that acquired glioma-like invasiveness through the combined FGF2 and BMP4 pathways were found to demonstrate EMT-related features." (PMID 25605251, 2015). "Immunohistochemical staining results for PDGFRA and FGF2 in glioma samples - Predominant staining intensity in each sample." (PMID 23630597, 2013). "Our findings suggest a role of FGF2 in regulating PDGFRA expression in the subset of gliomas with younger age at disease onset and longer patient survival regardless of their morphological diagnosis." (PMID 23630597, 2013). "In large numbers of glioma samples, our results showed that the pattern of FGF2 expression was similar to that of PDGFRA expression." (PMID 23630597, 2013). "We established 11 low passage glioma cell lines in N2 supported DMEM/F12 medium containing 2% FCS with a growth factor cocktail consisting of FGF2, PDGF-AA and SHH." (PMID 23630597, 2013). "In both data sets, the patterns of FGF2 expression were similar to those of PDGFRA expression; FGF2 expression was significantly enriched in low-grade gliomas, compared to high-grade gliomas (P<0.001, t test)." (PMID 23630597, 2013). "Our findings indicated FGF2 signaling as a potential intervening target in glioma subset with enriched PDGFRA expression." (PMID 23630597, 2013). "Nevertheless, the high molecular weight FGF2 isoform inhibits glioma proliferation and explains the radiation therapy resistance pathway." (PMID 22980038, 2012). "In the present report, we have used an siRNA-mediated gene knockdown approach to further elucidate the role of endogenous NUDT6 in the regulation of FGF2 expression and function in rat C6 glioma cells." (PMID 24704982, 2012). "The expression level of FGF-2 correlates with tumour grade, extent of anaplasia and clinical outcomes in glioma." (PMID 19018263, 2008).
glioma (continued). "Furthermore, several studies demonstrated that angiogenesis-related proteins such as VEGF, soluble endothelial growth factor receptor-1 (sVEGFR-1), and basic fibroblast growth factor (FGF-2) were elevated in circulation in patients with various glioma grades." (PMID 39063215, 2024). "These cells expressed stemness markers, could grow as spheres in a serum-free medium with growth factors EGF and FGF-2 and formed tumors in the brain of immunodeficient mice, reproducing histological features of human gliomas." (PMID 38392188, 2024). "This is supplemented with relatively high concentration of EGF and FGF2 to support the growth of glioma stem cells but may result in a rate of tumor cell proliferation that causes an artificially high sensitivity to both TMZ and irradiation." (PMID 37878712, 2023). "Moreover, the culturing medium is serum-free and is commonly supplemented with growth factors (EGF and FGF-2), which perpetuates the stem cell phenotypes frequently observed in glioma cells and establishes robust glioma stem cell (GSC) cultures." (PMID 37920169, 2023). "Although the loss of the FGF2 receptor gene is associated with a poor prognosis in glioma patients, FGF2 seems to be persistently expressed because it has been identified as an oncogenic factor in GBM, and its expression has been confirmed in other gliomas and meningiomas." (PMID 36142793, 2022). "In gliomas, both FGF2 and VEGF seem to have an essential role in regulating tumor growth and angiogenesis, indicating that their inhibition could be implemented as an antitumoral treatment." (PMID 35784465, 2022). "Also, it has been described that FGF-2 secreted by glioma cells augments the function of blood barrier function and contributes to therapy resistance, suggesting that FGF-2 has a further role in blood vessels already formed in the perivascular niche." (PMID 35269788, 2022). "High levels of FGF1 and FGF2 have been detected in glioma tissue relative to the normal brain." (PMID 33860438, 2021). "It is known that an increase in FGF-2 expression induced through autocrine production leads to increased proliferative activity, reduced apoptosis, and increased neovascularization, resulting in the maintenance of glioma stem cells." (PMID 34764346, 2021). "Interestingly, we found significantly increased expression of fibroblast growth factor 2 (FGF 2) in the serum EVs in glioma patients after surgery." (PMID 31410219, 2019). "Loilome and colleagues identified FGFR1 as a potential transducer of FGF2 effects on glioma cell proliferation, but whether other FGFRs also contribute was not directly tested." (PMID 31337028, 2019). "In 2006, inspired by NSC culture conditions, the Fine lab used serum-free, EGF/FGF-2-supplemented Neurobasal medium to cultivate primary glioma cells and found that these cells remained more similar to the parental tumors than those cultured in serum-containing DMEM medium." (PMID 28978189, 2017). "It's been shown that high FGF2 expression promotes human glioma's malignancy." (PMID 26056081, 2015). "Thus, FGF2 appears to be a key growth factor involved in regulating PDGFRA expression in glioma cells." (PMID 23630597, 2013). "Fibroblast growth factor 2 (FGF2) was able to maintain PDGFRA expression in glioma cells." (PMID 23630597, 2013). "FGF2 is widely expressed in normal brain astrocytes and also in gliomas." (PMID 23630597, 2013). "Glioma cells constitutively express high levels of nuclear FGF2 and FGFR1." (PMID 17049074, 2006). "Furthermore, stable transfection of SF-763 glioma cells with either FGFR1 or HMW FGF2 resulted in nuclear localization of the receptor and the growth factor and in increased proliferation." (PMID 17049074, 2006). "However, in glioma, Dach1 has been shown to transcriptionally suppress FGF2 expression." (PMID 38581619, 2024).
glioma (continued). "In addition, FGF2 can promote proliferation and cell survival through the activation of the Akt signaling pathway, which corroborates the fact that anti-FGF2 antibodies inhibited both anchorage-dependent and independent tumor growth of glioma U87MG and T98G cells." (PMID 35784465, 2022). "Furthermore, secretion of FGF2 by glioma cells enhances the blood-brain barrier function of endothelial cells, which may contribute to drug resistance." (PMID 33860438, 2021). "We therefore wonder whether FGF2 mediates the radioresistant effect of YAP on gliomas." (PMID 34127812, 2021). "Reprogramming COX-2, mPGES-1 and CYP4A mediated-AA metabolism in glioma by flavonoid ISL inhibits the angiogenic Akt- FGF-2/TGF-β/VEGF signaling through ceRNA effect of miR-194-5p and lncRNA NEAT1, and may serve as a novel therapeutic strategy for human glioma." (PMID 31438982, 2019). "Thus, although further in-depth characterizations on their transcriptomic and genomic profiles are required, gliomas with varying extent of PDGFRA expression could represent different molecular subtypes that respond differently to FGF2 signaling." (PMID 23630597, 2013). "We further assessed whether FGF2 can induce PDGFRA expression in glioma cells." (PMID 23630597, 2013). "Determinations of the other two proteins in glioma give the probability of the actual occurrence of the disease with a positive test result as 65.5% for VEGF-R2 and 89.1% for FGF-2." (PMID 38473833, 2024). "The blockade of FGF signalling by various means, amongst them FGF2 antibodies, siRNAs against FGFR1, or treatment with the FGFR/VEGFR inhibitor PD173074, reveals small but significant growth inhibitory effects in glioma cell lines." (PMID 33860438, 2021). "Inhibits the angiogenic Akt- FGF-2/TGF-β/VEGF signaling in C6 glioma cell line and the rat C6 glioma model." (PMID 34208562, 2021). "For example, GPC1 specifically forms a ternary complex with FGF2 and FGF-receptor 1 to promote cell signaling pathway activation in glioma vessel endothelial cells." (PMID 34957110, 2021). "SPIONs drive miR-485-5p overexpression in cells and inhibit endogenous Tie1 expression to downregulate the protein expression levels of Fgf2/GDNF/GFAP/BDNF and significantly weaken the in vivo and in vitro viability of gliomas." (PMID 32174801, 2020). "The lncRNA NEAT1 overexpression significantly reversed the decreased FGF-2, TGF-β and VEGF production induced by ISL in the U87 glioma cells, but miR-194-5p mimic attenuated these effects." (PMID 31438982, 2019). "Inhibition of COX-2, mPGES-1 and CYP4A by ISL decreased FGF-2, TGF-β and VEGF production in the C6 and U87 glioma cells with p-Akt downregulation, which was reversed by Akt overexpression." (PMID 31438982, 2019). "Herein, we demonstrated that inhibition of COX-2, mPGES-1 and CYP4A by ISL decreased FGF-2, TGF-β and VEGF production, and blocked glioma angiogenesis." (PMID 31438982, 2019). "Co-culture of BMSCs and glioma cells was found to inhibit angiogenesis in gliomas by down-regulating the expression of angiogenic markers such as PDGF-BB, IGF-1, FGF-2, and IL-1b." (PMID 31864321, 2019). "In vitro inhibition of COX-2, mPGES-1 and CYP4A by ISL decreased FGF-2, TGF-β and VEGF production in the C6 and U87 glioma cells, accompanied with the downregulation of p-Akt expression." (PMID 31438982, 2019). "In our literature search, we also found two papers that cultured primary glioma cells in media supplemented with a mixture of EGF, FGF-2 and PDGF." (PMID 28978189, 2017). "Further, we performed immunohistochemical staining of FGF2 and PDGFRA expression in cohort of 6 low-grade and 17 high-grade glioma samples." (PMID 23630597, 2013). "Using large glioma gene expression databases, we found that the expression of both PDGFRA and FGF2 were enriched in low-grade gliomas." (PMID 23630597, 2013). "Further, concordant expression patterns of FGF2 and PDGFRA were detected in glioma samples by immunohistochemical staining." (PMID 23630597, 2013).
glioma (continued). "FGF2-dependent PDGFRA expression appears to be a converged mechanism in normal glial development and glioma genesis." (PMID 23630597, 2013). "FGF2 and NUDT6 are co-expressed in rat C6 glioma cells, and ectopic overexpression of NUDT6 suppresses cellular FGF2 accumulation and cell cycle progression." (PMID 24704982, 2012). "We therefore enriched immature glioma cells by culturing single cell suspensions of freshly resected glioblastomas in serum-free medium supplemented with EGF and FGF-2 to favor the growth of undifferentiated cells." (PMID 21663643, 2011). "Furthermore, FGF-2 and VEGF expression in tumoral astrocytes and ECs was correlated to endothelial proliferation, tumoral angiogenesis and the degree of glioma malignancy." (PMID 35269788, 2022). "Blocking FGF2 signaling with the FGFR inhibitor AZD4547, which is evaluated in clinical trials as anticancer drugs, abolished YAP-conferred radioresistance and subsequent malignant progression of gliomas both in vitro and in vivo." (PMID 34127812, 2021). "Moreover, normal NSCs express EGFR and therefore, it seemed only natural to keep glioma cells in NSC media in vitro, which has EGF and FGF-2 as the main growth factors." (PMID 28978189, 2017). "Survivin, an angiogenesis-promoting protein, could activate the release of FGF-2, along with VEGF, in gliomas and thereby stimulate an increase in growth and proliferation in the tumors." (PMID 26977157, 2016). "Six out of the 17 interactions have been previously linked to invasion, migration or adhesion (EPHA4-Efnb3, SEMA5A-Plxnb3, AQP4-Dag1, FGFR1-Ncam1, FGF2-Sdc2, and APP-Aplp2) whereas only 3 interactions have been previously reported in glioma (SEMA5A-Plxnb3, AQP4-Dag1, and FGF2-Sdc2)." (PMID 25365423, 2014). "We speculate that FGF2 mediated signaling can potentially be manipulated to suppress PDGFRA expression and thereby inhibit niche factor-dependent glioma growth." (PMID 23630597, 2013). "Despite the strong reduction of γH2AX and the generally assumed anti-apoptotic nature of EGF and FGF-2, acute addition of these two cytokines did not reduce but even tended to enhance IR-induced apoptosis of differentiated glioma cells." (PMID 21663643, 2011). "However, it does not appear that FGF2 alone is crucial to the efficacy of 5-ALA-PDT as FGF2 added to U-105MG glioma cells did not have a stimulating or inhibitory effect on the final treatment outcomes." (PMID 39201395, 2024). "Because Src is involved in the signaling pathway evoked by EGF and FGF-2, and TAT-Cx43266–283 reduces Src activity in astrocytes and in glioma stem cells in vitro and in vivo, we aimed to confirm whether Src activity is also inhibited by TAT-Cx43266–283 in PC NPCs." (PMID 33238452, 2020). "Moreover, when comparing TAGs from the mature GBM phenotypes to TAGs from non-angiogenic gliomas, we observed a significant upregulation of Vegf, Angiopoietin 2 and Fgf2." (PMID 28173797, 2017). "More recently, the Uhrbom lab has established a biobank of glioma cell lines (The Human Glioblastoma Cell Culture Resource) with over sixty cell lines from surgical GBM samples, by growing them first as spheres and then as monolayer cultures in EGF/FGF-2 enriched media." (PMID 28978189, 2017). "FGF2 also induced PDGFRA expression in glioma cells with low or non-detectable PDGFRA expression." (PMID 23630597, 2013). "Thus, FGF2-dependent PDGFRA expression as observed in our study is likely an indirect effect; FGF2-dependent PDGFRA expression is probably applicable only to a specific subset of gliomas." (PMID 23630597, 2013). "To study whether FGF2 affects the expression of other gliogenic genes in addition to PDGFRA, we characterized the transcriptome profiles in two glioma cell lines cultured under the same conditions as above with or without FGF2 support." (PMID 23630597, 2013).